RNU6-839P (RNA, U6 small nuclear 839, pseudogene)
Gene: Small nuclear RNA gene on chromosome 10 (109,239,639 to 109,239,746, forward strand). Ensembl gene ENSG00000200217.
Homologues: Orthologues: chimpanzee U6 (98% identical), macaque U6 (92% identical), guinea pig U6 (72% identical), pig U6 (69% identical), dog U6 (69% identical). Paralogues in human: RNU6-15P (83% identical), RNU6-1011P (82% identical), RNU6-166P (82% identical), RNU6-17P (82% identical), RNU6-18P (82% identical), RNU6-41P (82% identical), RNU6-589P (82% identical), RNU6-647P (82% identical), RNU6-1 (81% identical), RNU6-1013P (81% identical), RNU6-1091P (81% identical), RNU6-1131P (81% identical), and 1282 more.